ZEB1 (zinc finger E-box binding homeobox 1)
Diseases named in the same sentence as ZEB1 in open-access papers (continued):
Sharing a sentence is not in itself a finding about the gene and the disease.
tumor (continued). "In our primary dataset, ZEB1 and ZEB2 were both up-regulated in six out of our eight ccRCC samples and, their expression levels were highly anti-correlated with the miR-200 family in both tumor and normal samples." (PMID 20420713, 2010). "There is evidence for an intricate network of microRNAs and the transcription factor ZEB1, which may not only regulate EMT, but also provide links to stem cell-like properties and chemoresistance of tumor cells." (PMID 24281218, 2010). "Furthermore, ZEB1 had ambiguous results, with some antibodies detecting heterogeneous expression and others detecting a complete absence of expression in the tumor cells." (PMID 41034989, 2025). "However, in our study, homozygous deletion of Zeb1 in macrophages neither weakened the pro-malignant effect of TAMs on tumor cells, nor did it reduce Mmp9 expression." (PMID 40595293, 2025). "In BC cells, the signaling pathways TNFα/NFκB and IL6/STAT3 are known to promote tumor progression via activation of key EMT-related transcription factors, such as Snail Family Transcriptional Repressor 1 (Snail1), Twist-related protein 1 (Twist1), and Zinc finger E-box binding homeobox 1 (ZEB1)." (PMID 40807456, 2025). "Considering that neutrophils constitute a prominent immunosuppressive cell population within the tumor microenvironment (TME), leading to T cell exclusion and unresponsiveness to antigen-specific stimulation, we investigated whether ZEB1 KD affects T cell response via neutrophils." (PMID 40924501, 2025). "For example, in breast cancer, miR-205 inhibits EMT by specifically targeting ZEB1 and ZEB2, thereby exerting tumor suppressor effects; Whereas, in cervical cancer cells, up-regulation of miR-205 can significantly target and inhibit CHN1 expression levels, thereby promoting tumor cell proliferation." (PMID 41001034, 2025). "Importantly, lymph node metastases were enriched in EMT-related gene programs and transcriptional circuits such as those driven by ZEB1, TWIST1, and TGIF2, which are known to fuel the mesenchymal shift in tumor cell states facilitating dissemination and survival in secondary sites." (PMID 41279557, 2025). "In addition, Zeb1 exerts its biological effects by inducing glycolytic activity via the PI3K/Akt/HIF-1α signaling axis in response to hypoxia, which contributes to the cultivation of an immunosuppressive tumor microenvironment." (PMID 39596288, 2024). "However, simultaneous deletion of both murine Zeb2 and Zeb1 in murine MLL-AF9 AML settings was found to significantly increase the overall survival of mice transplanted with MLL-AF9 secondary tumor cells compared with nontreated vehicle-treated controls." (PMID 39200378, 2024). "Whether this co-expression of SNAIL and ZEB1 may point to a prospective mixed/hybrid E/M phenotype of the tumor hybrids is not yet clear." (PMID 38139138, 2023). "SNAI2, TWIST1, and ZEB1 are the key regulatory genes contributing to the EMT process, where SNAI2 silencing substantially inhibits the EMT process, and overexpression of constitutively active TWIST1 in tumour cells promotes the acquisition of conspicuous EMT characteristics." (PMID 37686338, 2023). "While TJP1 expression in tumour cells is repressed in activated EMT, we found that the expression levels of SNAI2 and TWIST1 were significantly decreased in Ex-MaPac107 and the expression of ZEB1 was significantly increased in Ex-MaPac107 compared with Pri-MaPac107." (PMID 37686338, 2023). "The regulatory role of ZEB1 in NSCLC tumor malignancy has not been fully reported." (PMID 36644609, 2023). "The tumor immune microenvironment can also affect EMT programs, since FN1 and CRB3 marker genes are IFN-regulated ones (IRG = IFN-regulated gene); furthermore, some of the TFs of EMT are all regulated by IFN: SNAI1, TWIST1/2, ZEB1/2, SIX1, SOX4, and TCF4, according to the Interferome database." (PMID 36754910, 2023).
tumor (continued). "However, between these two TGFβ tumor types, the relationship between PD-L1 and ZEB1 expression is not as straightforward." (PMID 37638024, 2023). "Finally, ZEB1 belongs to the EMT-zing finger transcription factor family and is involved in crucial mechanisms related to the formation and development of the organs in the embryonic development, fibrosis and tumor progression." (PMID 38093305, 2023). "In addition, Zeb1 exerts its biological effects to induce glycolytic activity in response to hypoxia via the PI3K/Akt/HIF-1α signaling axis, which contributes to fostering an immunosuppressive tumor microenvironment (TME)." (PMID 35246504, 2022). "Besides, we validated the tumor-suppressive role of Biochanin A in CRC in vitro and in vivo, which could suppress the ZEB1-mediated progression and PD-L1 expression." (PMID 35242187, 2022). "Furthermore, ferroptosis-related genes with copy number amplification (including FADS2, NQO1, ABCC1, ACSF2, HMOX1, FANCD2 and SQLE) demonstrated higher expression in tumour tissues, and those with copy number deletion (including CRYAB, ACSL3, ZEB1) demonstrated lower expression in tumour tissues." (PMID 35145965, 2022). "However, neither HNRNPC nor ZEB1 expression showed any correlations with gender, age, or tumor location." (PMID 35963855, 2022). "However, despite limited metastatic burden, KP*C Zeb1 knockout mice have no significant survival benefit, likely because growth of the the primary tumour was not constrained." (PMID 36088504, 2022). "Conversely, treatment with a TGFβ signaling inhibitor reduced ZEB1 and SNAI2 levels and prevented the acquisition of mesenchymal marker expression and morphological features, thus linking mesenchymal differentiation in Rb with enhanced tumor cell invasion through the TGFβ/ZEB1/SNAI2 axis." (PMID 36291907, 2022). "Members of the miR-200 family primarily block EMT through direct repression of the EMT inducers ZEB1 and ZEB2, and impede tumor cell dissociation, migration, and invasion, which potentially combats the initial stages of the metastatic cascade, thus implicating the miRNAs’ tumor-suppressive effect." (PMID 35740906, 2022). "Indeed, ectopic ZEB1 expression promoted 393P tumor growth and metastasis, and Itga1 depletion abrogated ZEB1-induced cell proliferation on Col1-coated wells without affecting cell proliferation on plastic." (PMID 34874914, 2022). "Additionally, in our clones, ZEB1 and ZEB2—transcription factors that attach to the E-cadherin promoter region and inhibit the expression of this adhesion molecule—were upregulated, thereby increasing tumor cell motility." (PMID 35562862, 2022). "ZEB1 is a transcriptional factor in the epithelial-to-mesenchymal transition (EMT), being in a reciprocal feedback loop with miR-200a/b/c, and influencing cellular plasticity; the overexpression of ZEB1 or TGF-β1 stimulates EMT in cancer cells, leading to tumor progression." (PMID 35887090, 2022). "There is also significant in vitro and in vivo evidence indicating that EMT dynamics are influenced by cellular memory, and that this hysteretic control of EMT is governed by the miR-200s/ZEB1 negative feedback loop that was also observed in our cSCC tumor samples." (PMID 36012449, 2022). "Expression of ZEB1 in tumor cells leads to induction of EMT and stemness, and functions at both sides of the tumor-stroma interface by regulating the production of connective tissue growth factor (CTGF), hepatocyte growth factor (HGF), and interleukin 6 (IL6), to boost tumor progression." (PMID 35111082, 2021). "Thus, PRRX1 is more often positively correlated with ZEB1 and ZEB2 in patients’ HCC tumour samples." (PMID 34496784, 2021).
tumor (continued). "Zinc finger transcription factor ZEB1 is widely recognized as an important driver of tumour invasion, distant metastasis, drug resistance and radiation resistance by regulating the induction of epithelial‐mesenchymal transition (EMT) in tumour epithelial cells." (PMID 33960640, 2021). "To examine whether these tumor suppressive miRs are involved in the UTR interaction between Snail and Zeb1, we next overexpressed miR-34a or miR-200 together with luciferase vectors having a Snail or Zeb1 UTR, then measured the reporter activity and protein abundance in HCT116 cells." (PMID 34502497, 2021). "Instead, tumor-specific and context-dependent activation of subset of genes with distinct functions (e.g., SPARC, FN1, MMP7, ZEB1, ECM1) synergistically promoting, for example, collective cell migration upon interaction with the stromal microenvironment, may represent a more likely scenario." (PMID 34036938, 2021). "The number of Zeb1+ tumor cells also showed weak negative correlation with the number of TLS." (PMID 36860286, 2021). "Furthermore, our result indicated that miR-200a may inhibit tumor progression by interacting with CDK6 and ZEB1." (PMID 34796112, 2021). "Hence, the molecular mechanism of ZEB1 stability in tumor cells, which contribute to the progression of HCC, is not fully understood." (PMID 33649471, 2021). "Besides being a key contributor to the regulation of cancer cell differentiation and metastasis, the potential role of ZEB1 in the modulation of tumor chemoresistance is not yet fully understood." (PMID 32266287, 2020). "Zeb1 belongs to the zinc family of transcription factors, which suppress the expression of cell polarity factors and activate matrix metalloproteinases (MMP), thus promoting remodeling of the basement membrane and invasion of tumor cells to the surrounding tissue." (PMID 33379356, 2020). "Therefore, miR-128 regulated the infiltration of anti-tumor immune cells, including DCs, CD8+ T cells, and NKT cells, in the immune microenvironment through the ZEB1/CD47 axis, accompanied by the inhibition of the EMT process through ZEB1, ultimately inhibiting tumor growth and metastasis." (PMID 32536914, 2020). "For both cell line and tumor pieces, evaluation of gene expression demonstrates high endogenous expression of select mesenchymal genes (VIM, cMYC, FRA1, SNAI1 and SLUG), and low endogenous expressions of epithelial gene CD24 and mesenchymal genes TWIST and ZEB1." (PMID 30845999, 2019). "Notably, we identified new downstream target genes in 925 upregulated genes, including ZEB1, POU5F1, and MED1, which could be important factors in tumor metastasis and the maintenance of CSCs." (PMID 30674889, 2019). "Moreover, ZEB1 and ZEB2 staining were used to detect the EMT in xenografted tumor tissues." (PMID 31429770, 2019). "Whether staining was positive or negative for CAM5/CAM6/E-cad or E-cad/ZEB1 was evaluated in tumor cells." (PMID 31331982, 2019). "Since in our GSCs derived from patients’ tumor TGFβ had a behavior similar to that shown in GBM cell lines, i.e., as for ZEB1 and invasion increase, we wondered whether the effects caused by TGFβ and also by BzATP in our GSCs could be mediated by the same signal transduction pathway." (PMID 31905754, 2019). "This might explain why ZEB1 expression was not relevant to tumor size, Ki-67 level or other clinical factors in our study." (PMID 30976202, 2019). "Thus, the finding that ZEB1 is regulated by miR551b has a huge potential impact on research on the EMT and cancer metastasis and suggested that miR551b is a good therapeutic alternative for inhibiting the EMT and tumor progression in CRC." (PMID 31137914, 2019). "Furthermore, ZEB1 deletion in MaECs had no impact on metastatic lung nodule formation or tumour grading." (PMID 31324807, 2019).
tumor (continued). "We studied a retrospective cohort of 160 consecutive surgically treated NSCLC patients with available frozen tumor samples for expression of EMT markers (CDH1, CTNNB1, CDH2, and VIMENTIN), inducers (TGFB1, c‐MET, and CAIX), and transcription factors (EMT‐TF:SNAI1, SNAI2, ZEB1, TWIST1, and TWIST2)." (PMID 29845746, 2018). "miR-200c was recently identified as a repressor of epithelial-mesenchymal transition (EMT) via directly targeting ZEB1, while ZEB1 suppresses miR-200c transcription; thus, miR-200 and ZEB1 may oppose each other to control EMT program, tumor invasion, and metastasis." (PMID 29593314, 2018). "In addition, we utilized ZEB1 in decision curve analysis (DCA) to determine if this molecular marker provides a benefit in clinical decision making over the standard evaluation of utilizing age and tumor grade." (PMID 30705664, 2018). "However, we found that ZEB-1 was strongly expressed in endothelial, pericytic as well as tumor cells in all WHO grades (data not shown)." (PMID 29844871, 2018). "Under hypoxic conditions, the tumor microenvironment activates major EMT-triggering pathways (e.g., TGFβ signaling, Notch signaling) that facilitate tumor growth and metastasis, and HIF modulates major transcription factors (e.g., TWIST, SNAIL, SLUG, SIP1, ZEB1) that regulate EMT." (PMID 29593568, 2018). "In tumours the transcriptional repressor ZEB1 has been found to repress miRs 200a 200b and 429 that are thought to function to maintain epithelial differentiation, and ZEB1 and miR200 are interconnected via a double negative feedback loop." (PMID 29556478, 2018). "Tumor cells from KPC mice were highly heterogeneous, leading toestablishing distinct epithelial and mesenchymal cell lines from these cells.Consistent with experimental data, epithelial cells expressed high ESRP1 and lowZEB1, while mesenchymal cells expressed high ZEB1 and low ESRP1." (PMID 31069317, 2018). "This suggests that ZEB1 aberrations might be related to disease onset rather than to tumor progression." (PMID 30518749, 2018). "Furthermore, in the 22Rv1 cell line, derived from primary tumor and lacking RAS mutations, no SDC-1 repression by ZEB1 was observed." (PMID 30065348, 2018). "Furthermore, we performed a correlation study between the expression of circ-ZEB1.33 and miR-200a-3p in tumor tissues, significantly negative correlation was found." (PMID 30123094, 2018). "In addition to activating the JAK/STAT3 pathway via phosphorylation of STAT3, the IL-6/IL-6R interaction leads to low E-cadherin expression and high vimentin expression as well as upregulated expression of Snail, ZEB1, ZEB2, Twist and other transcription factors that promote tumor metastasis." (PMID 30157906, 2018). "In some tumor types, it blocked EMT and tumor progression, while in others induced EMT-TFs expression and EMT, like we observed in the induction of SNAI1, SNAI2 and ZEB1 expression in MCF7 cells after 5-aza treatment alone or in combination with the SIRT1 inhibitor." (PMID 30445998, 2018). "Furthermore, despite the ability of the miRNA-200/ZEB1 axis to regulate both EMT and PD-L1 expression in tumor cells, our findings strongly suggest that DSRCTs fall into the subgroup of “non-inflamed tumor types” that are closely associated with MErT/EMT and stem-like-traits." (PMID 28415643, 2017). "Moreover, Twist1 and ZEB1 could promote CAF hyperproliferation by blocking cell cycle control through repression of cyclin‐dependent kinase inhibitors, as described for tumour cells." (PMID 28544627, 2017). "ZEB1 was mainly localized to mesenchymal cells (60/60), not tumour cells (0/60)." (PMID 29115924, 2017). "Therefore, our results indicated that ZEB1/Ngn3 signaling may determine the replenishment of the breast CSC pool and promote tumor initiation." (PMID 28903350, 2017). "Also, ZEB1 and Twist immunostainings were correlated with grade: if both ZEB1 and Twist immunostaining was negative, then tumor grade was low in 100 % of the cases." (PMID 26951092, 2016).
tumor (continued). "However, evaluation of a number of genes (Zeb1, Zeb2, Twist, vimentin, etc) associated with EMT did not support the idea that SPC-IGFIR-Akt2−/− tumor cells had undergone EMT." (PMID 26654940, 2016). "Using our well-defined KP tumor cell model and human NSCLC cell lines in 2D/3D tissue culture models and in vivo studies, we found that integrin β1-collagen I interaction drives ECM-mediated FAK signaling and is required for Zeb1-dependent EMT, invasion and metastasis." (PMID 26728244, 2016). "Recently, Pier Paolo Pandolfi and colleagues found miR-22 promotes the EMT, tumor invasion and metastasis of normal and cancer mammary stem cells by targeting TET1, TET2 and TET3; miR-22 overexpression enhances some stemness and EMT-related genes expression, such as BMI1, ZEB1 and ZEB2." (PMID 26349457, 2016). "Notably, ZEB1 was repressed in nearly all tumours from never smokers (15 out of 16), a significantly higher frequency of repression than that observed in smokers (Fisher's exact text, P<0.05)." (PMID 27456471, 2016). "In our study, ZEB1 immunostaining was heterogeneous in 25 cases (62.5 %) and homogeneously positive in 1 case, but after attribute selection methods, ZEB1 immunostaining was a non-relevant variable for ITH classification as well as for tumor grade classification." (PMID 26951092, 2016). "The role of ZEB1 in cell proliferation and tumor growth is not fully understood." (PMID 27705917, 2016). "Recently, we published our findings that the miR-200/ZEB1 negative-feedback loop regulates CD8+ tumor-infiltrating lymphocytes by directly targeting PD-L1 expression, which strongly supports the idea that modulation of the immune system is a prerequisite to cancer metastasis." (PMID 26395571, 2015). "Moreover, our data reveal that miR-150 may function as a tumor suppressor and modulate EOC cell proliferation, and invasion by directly and negatively regulating ZEB1, implying the re-expression of miR-150 might be a potential therapeutic strategy for EOC." (PMID 25090005, 2014). "Histology, tumor grade, and metastatic lymph nodes did not affect ZEB1 scores." (PMID 24216980, 2013). "The majority of tumor cells in our CRCLM tumor model did not express ZEB1." (PMID 23153292, 2012). "The findings may be due to the fact that twist and zeb1 positive cells in the stroma represent a mixture of cell types, one proportion representing non-neoplastic activated fusiform fibroblastic cells, the other being EMT transformed tumor cells." (PMID 21324165, 2011). "Furthermore, the investigation of ZEB1 mediated epithelial-to-mesenchymal transition (EMT) induced tissue alterations and regulation of the WNT signalling pathway, which is crucial for stem cell maintenance, offering non-invasive insights into tumor progression and stromal interactions." (PMID 40856386, 2025). "In addition, CCL5 secreted by CAFs promotes metastasis by activating the HIF1α/ZEB1 axis in HCC cells, whereas herbal components such as glycyrrhizic acid may inhibit the interaction of CAFs with tumour cells and reduce the release of immunosuppressive factors." (PMID 40495147, 2025). "Importantly, though, with our PCLS and in situ data, we cannot distinguish whether the ZEB1-dependent CTL abundance (in situ) and the CCR2/CCR4-dependent tumor control (PCLS) are regulated by a direct recruitment of CD8 + T cells by CCL2 and/or CCL22 or other alternative mechanisms." (PMID 40595293, 2025). "Molecularly, Snail, and Zeb1 serve as EMT transcriptional factors and produce chemokines to attract immunosuppressive cells or promote the expression of immunosuppressive checkpoint molecules, which may lead to the tumor immunosuppressive microenvironment in SCLC‐V subtype." (PMID 37789961, 2023).